AR (androgen receptor)
Diseases named in the same sentence as AR in open-access papers (continued):
Sharing a sentence is not in itself a finding about the gene and the disease.
leukemia (15 papers, 2016 to 2025). A malignant (clonal) hematologic disorder, involving hematopoietic stem cells and characterized by the presence of primitive or atypical myeloid or lymphoid cells in the bone marrow and the blood. "Previously, small molecules targeting Menin-MLL interaction have been proposed as a therapeutic approach with promising results in leukemia and PC AR-positive models." (PMID 34711954, 2022). "In leukemia, AR expression is silenced, in part, due to increased methylation of CpG islands in the AR promoter." (PMID 26880966, 2016). "Circumstantial evidence suggests that the AR may also play a role in leukemia, breast, and brain CSCs." (PMID 26880966, 2016).
viral infection (15 papers, 2016 to 2024). "TMPRSS2 is a target of the androgen receptor (AR), and this may explain the higher male susceptibility toward this viral infection." (PMID 33584306, 2020). "A more in-depth analysis is warranted to investigate how testosterone and AR activity regulate gut immunity during viral infections." (PMID 39451246, 2024). "The study underscores the critical roles of AR signalling in viral infection and lays the foundation for antiandrogenic drug application in COVID‐19 therapeutics." (PMID 37218396, 2023). "Suppressive effects of androgens and AR can facilitate a potent viral infection and a cytokine storm." (PMID 33915795, 2021). "Thus, drugs inhibiting AR signalling were found to reduce viral infection in hESC‐derived lung organoids." (PMID 37218396, 2023). "The TGFβ signaling module consists, besides the TGFβ–pathway, of related pathways regulating SMAD2/3 signaling, HIF-1 alpha transcription, coregulation of androgen receptor activity, FOXA1 transcription and some pathways related to viral infections." (PMID 26701206, 2016). "Furthermore, another study has shown that α-5 reductase inhibitors, another class of androgen inhibitors decreasing the amounts of DHT in cells and inhibiting the AR signaling, reduced TMPRSS2 expression and viral infection in lung organoids." (PMID 36834705, 2023).
endometriosis (14 papers, 2012 to 2025). The growth of functional endometrial tissue in anatomic sites outside the uterine body. "These PCOS phenotypes, as well as endometriosis, are caused by dysregulation of sex hormone receptors, namely ER, PR and AR." (PMID 35885010, 2022). "Additionally, a bioinformatic analysis identified AR as a key endometriosis-associated transcription factor, with 373 target AR genes significantly differentially expressed in endometriotic lesions compared with those in the normal endometrium." (PMID 40063300, 2025). "In addition, a study identified AR as an endometriosis-associated transcription factor, and 373 AR target genes were differentially expressed in endometriosis compared to normal endometrium." (PMID 36358974, 2022). "This suggests that the CAG repeat polymorphisms of AR may serve as useful markers to predict endometriosis." (PMID 36358974, 2022). "What is more, AR gene polymorphism may be related to the pathogenesis of endometriosis." (PMID 36358974, 2022). "Of course, the further research on the roles of AR in endometriosis development and how these genes influence AR signaling in endometriosis still needs to be further explored." (PMID 36860677, 2023). "In the eutopic endometria of endometriosis patients, AR, progesterone receptor (PGR) and progesterone receptor membrane component 1 (PGRMC1) showed decreased expression compared with normal endometria, with log2FC<1 in both the GSE51981 and GSE120103 datasets." (PMID 36860677, 2023). "And the positive expression of AR in the main cell types for endometriosis development can also be detected, especially in endometrial stromal cells." (PMID 36860677, 2023). "Considering the role of AR in the endometrial aberrations of endometriosis patients, we identified 94 interactors of AR using GPS-Prot and Biogrid." (PMID 36860677, 2023). "Endometrial stromal cells are the main cell type expressing AR in endometrial tissues, and they are also an important cell type for endometriosis development." (PMID 36860677, 2023). "Instead, the gene sets that can modulate AR signaling were involved in endometriosis development and displayed good predictive value, which also indicates the importance of AR signaling on disease occurrence and provides new targets for the disease." (PMID 36860677, 2023). "The network of the DEGs between normal endometrium and those of patients with endometriosis contained 683 nodes and 5105 edges, with AR, PGR and PGRMC1 involved in the network construction." (PMID 36860677, 2023). "These gene sets also showed the moderate clustering of endometriosis organoids, although at times, endometriosis clustered with cystic hyperplasia or one endometriosis participant clustered with controls (Regulation of Androgen Receptor Signaling)." (PMID 34945786, 2021). "First, danazol, an androgen analog used for treatment of endometriosis, directly binds to the AR of endometriotic tissue and decreases the expression of Bcl-2 (a suppressor for apoptosis), resulting in the cell death of endometriotic tissue." (PMID 23139742, 2012). "The search for the specific targets of AR signaling regulation in endometriosis may provide the new insight for the development of treatment options." (PMID 36860677, 2023). "Androgen receptor (AR), as the hub gene of endometrial aberrations in endometriotic patients, showed positive expression in the main cell types for endometriosis development, and its decreased expression in the endometrium of endometriotic patients was also confirmed by immunohistochemistry (IHC)." (PMID 36860677, 2023). "The interaction between AR and PR in mediating endometrial effects in endometriosis pathogenesis remains unclear due to contradictory findings in different publications." (PMID 35885010, 2022). "A more detailed investigation on the specific ER agonists or androgen receptor antagonists could elucidate the receptor-specific mechanisms and their interactions in the modulation of endometriosis." (PMID 33987175, 2020).
endometriosis (continued). "Our results also support the role of AR in the pathophysiology and therapeutics of endometriosis." (PMID 23139742, 2012). "Interestingly, polymorphic CAG repeats of AR genes may be related to the pathogenesis of endometriosis." (PMID 40063300, 2025). "Furthermore, the potential roles of AR in endometriosis development provide us new insights into the disease, which may lead to the development of novel treatment strategies." (PMID 36860677, 2023). "The results showed that, compared with normal endometria, the expression of AR, PGR, and PGRMC1 in eutopic endometria derived from patients with endometriosis was decreased." (PMID 36860677, 2023). "What's more, both AR and PGR were identified as the hub genes between normal endometria and those of endometriosis patients, and ESR1 was selected as the hub gene between eutopic and ectopic endometria from the same patients." (PMID 36860677, 2023). "Considering the lack of research on AR in endometriosis, we next explored the expression of AR in human tissues and cells to explore the possibility of AR involvement in the formation of endometriosis." (PMID 36860677, 2023).
Hirsutism (14 papers, 2011 to 2025). Abnormally increased hair growth referring to a male pattern of body hair (androgenic hair). "MicroRNAs and gene variants in the androgen receptor gene appear to be promising for understanding the pathophysiology of hirsutism." (PMID 36010272, 2022). "Shorter length of the polymorphic CAG repeats of the androgen receptor (AR) gene may be associated with increased activity of the receptor leading to hirsutism." (PMID 29584789, 2018). "Conversely, the affinity of spironolactone for the androgen receptor can therapeutically be exploited in hirsutism, i.e., excessive body hair in females, as this is dependent on androgen receptors." (PMID 41301427, 2025). "The androgen receptor (AR) is the key protein controlling cellular androgen sensitivity, thus making it a promising candidate modifier of the degree of hirsutism." (PMID 29584789, 2018). "Shorter CAG repeat polymorphisms of the androgen receptor gene may be associated with increased activity of the receptor, leading to PCOS and hirsutism." (PMID 36010272, 2022). "Whereas androgen signalling is essential for hair biology and has been shown to regulate hair growth and cycling at different body sites, GnRH signalling antagonises androgen receptor signalling at androgen-sensitive body sites in women, and GnRH antagonists are an effective treatment for hirsutism." (PMID 28228108, 2017). "Indeed, the pathogenesis of hirsutism is complex and depends on several factors, such as the idiosyncratic reaction of the pilosebaceous unit to androgens, increased levels of androgens, androgen receptor activity, and a possible deficit in the production of 5-α reductase and other key enzymes." (PMID 39941345, 2025).
Klinefelter syndrome (14 papers, 2008 to 2025). A sex chromosome disorder caused by the presence of an extra X chromosome in the male karyotype. "Men with Klinefelter syndrome, the most frequent form of male hypogonadism, are often diagnosed with Hashimoto’s thyroiditis, while the (CAG)n repeat polymorphism, determining the sensitivity of the androgen receptor, correlated with the age of onset of Hashimoto’s thyroiditis." (PMID 34106452, 2021).
autism (13 papers, 2012 to 2023). Persistent deficits in social interaction and communication and interaction as well as a markedly restricted repertoire of activity and interest as well as repetitive patterns of behavior. "The female-specific gene TCF4 is a reported autism-associated gene and is associated with coregulation of androgen receptor activity." (PMID 32066658, 2020). "There was no statistically significant univariate, logistic association between autism and testosterone or androstenedione, which act via the androgen receptor." (PMID 31358906, 2020). "Moreover, AR polymorphisms appear to be associated with sociality, aggressiveness, and depression or autism." (PMID 24348454, 2013). "This work suggests that routes of influence via the AR may be more likely implicated in autism." (PMID 30104728, 2020). "KMT2C (lysine methyltransferase 2C) is an autism candidate gene and downstream target gene of AR." (PMID 36803626, 2023). "Nevertheless, one suggestion might be that epitestosterone has the effect of a competitive inhibition on the androgen receptor, which would probably help to explain the higher prevalence of autism in boys as compared to girls." (PMID 33535392, 2021). "During androgen-receptor-(AR-) dependent gene activation, this sequence may produce AR-dependent gene overactivation which may partly explain the male predominance of autism." (PMID 24151554, 2013). "Furthermore, variations on the AR gene were found in females with autism." (PMID 26066795, 2015). "AR-dependent gene overactivation in conjunction with a DNMT mechanism for methylating oxytocin receptors could produce high arousal inputs to the amygdala resulting in aberrant socialization, a prime characteristic of autism." (PMID 24151554, 2013).
erectile dysfunction (13 papers, 2013 to 2024). Persistent or recurrent inability to achieve or to maintain an erection during sexual activity. "Injections of the AR agonist testosterone are used to treat male patients with delayed puberty or impotence." (PMID 29181019, 2017). "Men with acromegaly have a high prevalence of erectile dysfunction, but it does not appear to be correlated with treatments, testosterone levels and AR/ER-beta signaling." (PMID 37306894, 2024).
non-small cell lung carcinoma (13 papers, 2014 to 2024). A group of at least three distinct histological types of lung cancer, including non-small cell squamous cell carcinoma, adenocarcinoma, and large cell carcinoma. "The tri-methyl selective KDM4A/JMJD2A demethylase is an AR coregulator expressed in PCa and is a determinant of mTOR inhibitor sensitivity in non-small cell lung cancer patients." (PMID 26461474, 2015). "In non-small cell lung cancers, the overexpression of AR has been detected in patients, and the knockdown of AR in cell lines could suppress tumorigenicity." (PMID 35053220, 2022). "Trials of anamorelin for cachexia in non-small cell lung cancer (NSCLC) and enobosarm, an androgen receptor modulator, have shown promise but have not yet achieved FDA approval in the US." (PMID 36358681, 2022).
Stroke (13 papers, 2006 to 2024). Sudden impairment of blood flow to a part of the brain due to occlusion or rupture of an artery to the brain. "Seemingly, both too low and too high levels of AR signaling can have implications on the risk of stroke." (PMID 37571268, 2023). "We have investigated the C-106T polymorphism in the promoter region of the AR gene as a candidate gene for susceptibility to diabetic macroangiopathy, and found that the CT or TT genotype is associated with increased risk of stroke in Type 2 diabetic patients." (PMID 16911628, 2006). "Compared with these gene variants, the adjusted OR we observed in this study suggests that the AR gene exerts a stronger effect on the risk of stroke." (PMID 16911628, 2006). "We showed that the CT and TT genotypes and the T allele of the C-106T polymorphism in the AR promoter region are thought to be a risk factor for stroke." (PMID 16911628, 2006). "In conclusion, we have found that the C-106T polymorphism in the promoter region of the AR gene is associated with an increased risk of stroke in Type 2 diabetic patients." (PMID 16911628, 2006). "In contrast, the CT + TT genotype and the T allele of the AR gene were associated with an increased risk of stroke, and the significance of these genotypes remained high even after adjustment for other risk factors." (PMID 16911628, 2006). "However, prospective intervention studies with aldose reductase inhibitors would be required to confirm the influence of the AR gene polymorphism and AR content on the development of stroke." (PMID 16911628, 2006). "Thus, it cannot be excluded that this AR polymorphism is in linkage disequilibrium with an unidentified polymorphism strongly related to stroke risk." (PMID 16911628, 2006). "Our results suggest that the CT or TT genotype of the AR gene might be a genetic marker of susceptibility to stroke in Type 2 diabetic patients." (PMID 16911628, 2006). "There is evidence that low endogenous AR levels can contribute to higher incidence of stroke and that androgen treatment worsens stroke outcomes under supra-physiological androgen doses." (PMID 37571268, 2023). "There are various mechanisms by which high levels of AR signaling can contribute potentially to stroke." (PMID 37571268, 2023). "On the contrary, most previous studies showed that testosterone confers deleterious effects to both adult castrates and gonadally intact rodents during stroke and these effects are abrogated by administration of the AR antagonist flutamide." (PMID 23401794, 2013). "Like other CVDs, the effect of AR signaling on stroke incidence is paradoxical." (PMID 37571268, 2023). "However, there are upregulations of AR expression following stroke, non-alcoholic fatty liver disease, diabetic retinopathy as well as diabetic peripheral neuropathy." (PMID 36352421, 2022). "Regarded as the effectors of mi-RNA, targetgenes such as SP1, AR, and EGFR had the largest number of edges in the network, indicating that they were closely associated with other genes and played significant roles in stroke." (PMID 26830013, 2016). "This suggests that there are differences in the pathogenesis of ischaemic heart disease and stroke, which might explain our lack of association of the AR gene with ischaemic heart disease." (PMID 16911628, 2006). "Therefore, it may be speculated that polymorphisms of the AR gene, concomitant with an increase in erythrocyte AR content, would increase vulnerability of brain arteries resulting in stroke." (PMID 16911628, 2006). "AR is a ligand-activated transcription factor that mainly affects cell proliferation and differentiation in target tissues, and a study has demonstrated that overexpression of AR is neuroprotective in MCAO mice, potentially contributing to gender differences in human stroke outcomes." (PMID 34603472, 2021).
Alzheimer disease (12 papers, 2016 to 2023). A progressive, neurodegenerative disease characterized by loss of function and death of nerve cells in several areas of the brain leading to loss of cognitive function such as memory and language. "Another study showed that lower AR(CAG)n in men with low testosterone is associated with Alzheimer’s disease, suggesting that high expression of androgen receptors in the absence of androgen has detrimental effects." (PMID 32593802, 2020). "SARMs (selective androgen receptor modulators) are being explored as a potential therapy for Alzheimer’s disease." (PMID 37570816, 2023). "Abiraterone acetate reduced the risks of Alzheimer's disease and Parkinson's disease conferred by GnRH agonists, whereas the risk for ALS was reduced by androgen receptor inhibitors." (PMID 35293700, 2022). "A recent transcriptome meta-analysis revealing the key role of AR in Alzheimer’s disease highlights the relevance of such an approach." (PMID 26849367, 2016). "Although it is known that the full-length androgen receptor is expressed in the hippocampus, our data showed lack of full-length androgen receptor expression in frozen hippocampal postmortem tissue from individuals diagnosed with Alzheimer’s disease." (PMID 32223745, 2020). "Thus chaperone functionality in Alzheimer’s disease and the possibility of AR-12 or analogues of AR-12 being developed as a therapeutic for this disorder should be considered if supported by appropriate in vivo preclinical models." (PMID 27957385, 2016).
apocrine tumors (12 papers, 2012 to 2025). "In molecular apocrine tumors, characterized by ER-negative and AR-positive status, androgens have an established oncogenic role." (PMID 37681860, 2023). "Combination of HMGCS2 with steroidal profile (AR+/ER-/PR-) offers greater sensitivity to detect breast apocrine tumors compared to steroidal profile alone." (PMID 25389781, 2014). "In molecular apocrine tumors, in addition to the classical androgen-induced signaling transduction, an overexpression of HER2 associates with AR positivity that suggests a cross-talk between the AR and HER2 signaling pathways." (PMID 37681860, 2023). "The enrichment of apocrine tumors among the Mayo TNBC cohort suggests that the role of AR still warrants further investigation." (PMID 35734391, 2022). "Thus, HMGCS2+/AR+/ER-/PR- profile exhibited a significantly higher sensitivity as compared with the AR+/ER-/PR- phenotype, which only provides a sensitivity of 54,17% for apocrine tumors." (PMID 25389781, 2014). "By definition, apocrine tumors express AR and GCDFP-15 while lacking ER, PR, BCL-2, and GATA3." (PMID 41293328, 2025).